OR2I1 (olfactory receptor family 2 subfamily I member 1 (gene/pseudogene))
Description:
Odorant receptor.
Synonyms: OR2I1P; OR2I3P; OR2I4P; HS6M1-14; OR2I2; OR2I5P; OR2I6; OR2I7P; OR2I8P; OR2I9P; OR6-1; OR6-34
Tractability: Antibody: UniProt places it where antibodies can reach, with high confidence; UniProt predicts a signal peptide or a membrane-spanning region; its Gene Ontology location is reachable by antibodies, with medium confidence.
Gene: Protein-coding gene on chromosome 6 (29,550,407 to 29,557,773, forward strand). Ensembl gene ENSG00000237988.
Subcellular location: Cell membrane
Pathways (Reactome):
Sensory Perception: Expression and translocation of olfactory receptors
Gene Ontology:
Molecular function: olfactory receptor activity; G protein-coupled receptor activity
Biological process: detection of chemical stimulus involved in sensory perception of smell; G protein-coupled receptor signaling pathway
Cellular component: plasma membrane; membrane
Homologues: Orthologues: macaque OR2I1P (95% identical), mouse Or2i1 (82% identical), rat Or2i1 (81% identical), guinea pig OR2I1 (78% identical). Paralogues in human: OR2Y1 (54% identical), OR2G6 (52% identical), OR2G3 (51% identical), OR2C3 (50% identical), OR2H2 (50% identical), OR2J1 (50% identical), OR2G2 (49% identical), OR2J2 (49% identical), OR2J3 (49% identical), OR2H1 (48% identical), OR2W3 (48% identical), OR2C1 (47% identical), and 80 more.
Diseases named in the same sentence as OR2I1 in open-access papers:
OR2I1 is named in the same sentence as 5 diseases in open-access papers, as found by Europe PMC text mining. Sharing a sentence is not in itself a finding about the gene and the disease.
OR2I1 shares sentences with these, for which no sentence is quoted: adenoma (1 paper); carcinoma (1); kidney cancer (1); liver disease (1); tumor (1).